PRKAG3 (protein kinase AMP-activated non-catalytic subunit gamma 3)
Description:
AMP/ATP-binding subunit of AMP-activated protein kinase (AMPK), an energy sensor protein kinase that plays a key role in regulating cellular energy metabolism. In response to reduction of intracellular ATP levels, AMPK activates energy-producing pathways and inhibits energy-consuming processes: inhibits protein, carbohydrate and lipid biosynthesis, as well as cell growth and proliferation. AMPK acts via direct phosphorylation of metabolic enzymes, and by longer-term effects via phosphorylation of transcription regulators. AMPK also acts as a regulator of cellular polarity by remodeling the actin cytoskeleton; probably by indirectly activating myosin. The AMPK gamma3 subunit is a non-catalytic subunit with a regulatory role in muscle energy metabolism. It mediates binding to AMP, ADP and ATP, leading to AMPK activation or inhibition: AMP-binding results in allosteric activation of alpha catalytic subunit (PRKAA1 or PRKAA2) both by inducing phosphorylation and preventing dephosphorylation of catalytic subunits. ADP also stimulates phosphorylation, without stimulating already phosphorylated catalytic subunit. ATP promotes dephosphorylation of catalytic subunit, rendering the AMPK enzyme inactive.
Synonyms: AMPKG3; SMGMQTL
Tractability: Small molecule: a drug acting on it is in phase 2 or 3 trials; a high-quality ligand is known. PROTAC: ubiquitination databases record sites on it; a small molecule that binds it is known.
Safety:
Unwanted effects reported when the protein is acted on. In parentheses: how it was acted on, where the effect was seen, and who reports it.
heart disease (cardiovascular system; source: Force et al. (2011))
Gene: Protein-coding gene on chromosome 2 (218,819,050 to 218,832,086, reverse strand). Ensembl gene ENSG00000115592.
Subcellular location (Human Protein Atlas): Mitochondria; Nucleoplasm
Pathways (Reactome):
Autophagy: Lipophagy; Macroautophagy
Immune System: AMPK-induced ERAD and lysosome mediated degradation of PD-L1(CD274)
Neuronal System: Activation of AMPK downstream of NMDARs
Organelle biogenesis and maintenance: Activation of PPARGC1A (PGC-1alpha) by phosphorylation
Signal Transduction: Energy dependent regulation of mTOR by LKB1-AMPK
Vesicle-mediated transport: Translocation of SLC2A4 (GLUT4) to the plasma membrane
Gene Ontology:
Molecular function: protein binding; protein kinase binding; protein kinase regulator activity; AMP binding; AMP-activated protein kinase activity
Biological process: cellular response to nutrient levels; intracellular signal transduction; positive regulation of gluconeogenesis; regulation of cell cycle; regulation of glycolytic process
Cellular component: extracellular region; nucleotide-activated protein kinase complex; cytoplasm; cytosol; endoplasmic reticulum lumen; nucleoplasm; nucleus
Genetic constraint (gnomAD): Loss-of-function variants: 39 observed, 56.9 expected, observed/expected ratio (o/e) 0.69, 90% interval 0.53 to 0.89. The upper end of that interval is the gene's LOEUF score, 0.89, which puts it in group 3 of 6, group 1 being the genes least tolerant of losing a copy. Missense variants: 628 observed, 647.67 expected, observed/expected ratio (o/e) 0.97, 90% interval 0.91 to 1.04. Synonymous variants: 243 observed, 257.69 expected, observed/expected ratio (o/e) 0.94, 90% interval 0.85 to 1.05.
Homologues: Orthologues: chimpanzee PRKAG3 (99% identical), macaque PRKAG3 (96% identical), rabbit PRKAG3 (87% identical), mouse Prkag3 (85% identical), rat Prkag3 (84% identical), dog PRKAG3 (83% identical), guinea pig PRKAG3 (82% identical), pig PRKAG3 (80% identical), tropical clawed frog prkag3 (47% identical), zebrafish prkag3b (44% identical), zebrafish prkag3a (39% identical), Caenorhabditis elegans aakg-2 (26% identical), and 1 more. Paralogues in human: PRKAG2 (47% identical), PRKAG1 (40% identical).
Diseases named in the same sentence as PRKAG3 in open-access papers:
PRKAG3 is named in the same sentence as 26 diseases in open-access papers, as found by Europe PMC text mining. Sharing a sentence is not in itself a finding about the gene and the disease. The quoted sentences say what the papers report.
breast carcinoma (2 papers, 2025). "Another study associated PRKAG3 with the mammalian target of rapamycin (mTOR) pathway and breast cancer risk, particularly among patients with estrogen receptor-negative breast cancer." (PMID 40839607, 2025). "PRKAG3, a regulatory subunit of the AMP-activated protein kinase (AMPK) complex, has been associated with breast cancer risk in several studies." (PMID 40839607, 2025). "PRKAG3 is essential in regulating cellular energy, but its expression and role in breast cancer cells remain unclear." (PMID 39859448, 2025). "Because AMPK functions as a tumor suppressor by inhibiting the mTOR pathway, we hypothesized that the decreased PRKAG3 activity in mammary carcinoma may decrease the inhibitory effect of AMPK, leading to tumor growth." (PMID 40839607, 2025). "Among these, ABCC3, ACPP, PPP1CA, PRKAG3, and RNASEL exhibited interactions with several proteins, immune checkpoint markers, and chemotherapeutic drugs administered in both human breast cancer and FMC." (PMID 40839607, 2025). "We found that ABCC3, ACPP, PPP1CA, PRKAG3, and RNASEL were involved in the tumorigenesis of FMC and exhibited interactions with proteins and chemotherapeutic drugs relevant to both human breast cancer and FMC." (PMID 40839607, 2025).
cardiomyopathy (1 paper, 2020). A disease of the heart muscle or myocardium proper. "Expression data showing downregulation of AMPK regulator PRKAG3 could be indicative of altered glycogen storage, with glycogen storage disease and PRKAG2 (isoform of PRKAG3) mutation seen in some cases of cardiomyopathy." (PMID 31724174, 2020).
gastric ulcer (1 paper, 2022). An ulcerated lesion in the mucosal surface of the stomach. "Downregulation of Srm, Ryr-1, Eno3, Prkag3, and Eef1a2 genes involved in regulating arginine and proline metabolism, calcium signaling pathway, HIF-1 signaling pathway, oxytocin signaling pathway, and legionellosis are possibly involved in MD-4-mediated protection against gastric ulcers." (PMID 36292625, 2022).
sarcoidosis (1 paper, 2025). Sarcoidosis is a multisystemic disorder of unknown cause characterized by the formation of immune granulomas in involved organs. "While metformin was found to interact with PRKAG3, a gene significantly altered in both conditions, and exhibited cytotoxic effects on LC cells, the extent to which it might prevent malignant progression in high-risk sarcoidosis patients remains to be identified." (PMID 40797277, 2025). "The current findings, however, highlight its potential dual applicability, reinforcing the value of drug repurposing strategies in targeting converging molecular mechanisms, particularly involving PRKAG3 dysregulation in sarcoidosis LC overlapping conditions." (PMID 40797277, 2025). "Additionally, PRKAG3 was notably upregulated in sarcoidosis but decreased in LC patients." (PMID 40797277, 2025).
cancer (3 papers, 2023 to 2026). A tumor composed of atypical neoplastic, often pleomorphic cells that invade other tissues. "Conversely, the alteration of PRKAG3 in both diseases is likely linked to its role in regulating cellular energy metabolism and stress responses, critical processes that are frequently disrupted in chronic inflammatory conditions and cancer." (PMID 40797277, 2025). "Second, AKT regulates cancer cells by PAK1/ATF2/miR-132 signaling axis and PRKAG3 is a target gene of miR-132." (PMID 36766336, 2023).
tumor (2 papers, 2024 to 2025). "Low proliferative tumors (Ki-67 ≤ 43.4%) had higher expression of PRKAG3 compared to high proliferative tumor (Ki-67 > 43.4%, p = 0.03)." (PMID 40839607, 2025). "PRKAG3, as part of the AMPK complex, plays a role in immune cell function and has been implicated in promoting CD8 + T cell exhaustion, contributing to tumor immune escape." (PMID 40839607, 2025). "When comparing the 28 significant genes in ER+ tumor tissues and the 9 significant genes in ER+ adjacent normal tissues, 2 genes overlapped (HUS1 and PRKAG3)." (PMID 38886818, 2024).
PRKAG3 also shares sentences with these, for which no sentence is quoted: infection (2 papers); type 2 diabetes (2); cardiac hypertrophy (1); diabetes (1); glycogen storage cardiomyopathies (1); glycogen storage disease (1); heart disorder (1); Huntington disease (1); Hypertension (1); hypertrophic cardiomyopathy (1); kidney damage (1); left ventricular dilation (1); legionellosis (1); medulloblastoma (1); neurodegenerative disease (1); Obesity (1); Parkinson disease (1); steatosis (1); supraventricular tachyarrhythmias (1); triple-negative breast carcinoma (1).